RNU6-1252P (RNA, U6 small nuclear 1252, pseudogene)
Gene: Small nuclear RNA gene on chromosome 4 (52,494,849 to 52,494,952, forward strand). Ensembl gene ENSG00000199924.
Homologues: Orthologues: chimpanzee U6 (100% identical), rabbit U6 (90% identical), guinea pig U6 (86% identical). Paralogues in human: RNU6-698P (90% identical), RNU6-1117P (89% identical), RNU6-1145P (89% identical), RNU6-38P (89% identical), RNU6-1125P (88% identical), RNU6-116P (88% identical), RNU6-1316P (88% identical), RNU6-434P (88% identical), RNU6-1060P (88% identical), RNU6-1175P (88% identical), RNU6-1251P (88% identical), RNU6-15P (88% identical), and 1286 more.